STAT6 (signal transducer and activator of transcription 6)
Diseases named in the same sentence as STAT6 in open-access papers (continued):
Sharing a sentence is not in itself a finding about the gene and the disease.
infection (continued). "Absence of STAT6 signaling resulted in enhanced susceptibility to infection coinciding with increased parasite burden in the brain suggesting that M2 macrophages actively control infection." (PMID 25505468, 2014). "IL-4 can induce the activation of STAT1, STAT3, STAT5 and STAT6 on naïve and activated CD8+ T cells in vitro, but our infections studies with VV-HA-IL-4 indicated that STAT6 was indispensible for IL-4 mediated up-regulation of cell surface IL-4Rα expression on naïve and effector CD8+ T cells." (PMID 23383283, 2013). "Using a STAT6 reporter assay, we found that there was a significant increase in STAT6-inducing activity in the serum (56% increase; p<0.05) obtained from hamsters with active VL (56 days post-infection) compared to uninfected controls." (PMID 22275864, 2012). "Paralleling the STAT6 phosphorylation results, wild-type and complemented parasites, but not ΔROP16 tachyzoites, induced arginase-1 synthesis, a response detectable by immunoblotting for arginase-1 protein within 6 hr of infection." (PMID 21931552, 2011). "Consistently, CD23 expression following infection with T. gondii parasites may be due to their ability to induce the transcription factor STAT6, which is involved in the induction of Th-2 gene promotion including CD40, CD23 and IgE." (PMID 21526166, 2011). "Likewise, the authors reported STAT6-independent arginase-1 induction during infection with Type II ROP16-expressing parasites, a result that also stands in contrast to our findings." (PMID 21931552, 2011). "Since STAT3 is activated, we expected to detect differential expression of STAT3 target genes; however, other STAT proteins activated by E. chaffeensis, such as STAT5 and STAT6, also mediate inflammatory and oncogenic signaling and may be relevant during infection." (PMID 41115066, 2025). "In summary, we postulate that targeting E2f1, Myc, Pparγ and Stat6 in M2-like macrophages induces a shift towards immunostimulatory M1-like macrophages, which may support immune defense and hence improve therapy against infection." (PMID 32097424, 2020). "T. gondii possesses effector proteins that act on host cells, which are capable of inducing the activation of the STAT3, STAT6, and NF-κB pathways, thus leading to the production of many cytokines and immunomodulatory molecules that may interfere in infection latency." (PMID 31828046, 2019). "However, STAT6 KO mice elicit a blunted neutrophilic response after infection with pneumocystis." (PMID 28903780, 2017). "However, in the current study, viral load in organs and blood 7 days after infection did not consistently correlate with increased susceptibility, with the exception of STAT-6−/− mice." (PMID 25751266, 2015). "In addition, the course of infection and the phenotype of the infected cells do not appear to be affected by STAT6 deficiency." (PMID 26376185, 2015). "Stat6-deficient mice are viable, but suffer defects in the differentiation of several immune and non-immune cell types, exhibit increased susceptibility to infection by certain viral, bacterial and helminthic pathogens and show attenuated allergic responses." (PMID 24314139, 2013). "Therefore, STAT6 activation during infection is entirely dependent upon the parasite kinase." (PMID 21931552, 2011). "It is possible that T. gondii (types I and III) ROP16 activates M2 macrophages by activating STAT6, which reduces the secretion of proinflammatory factors such as IL12 in the early infection stage, thus helping to reduce the host responses." (PMID 34986898, 2022). "Several cytokine response elements including STAT5B, STAT6, and IL10RB contributed to enrichment of a number of pathways relating to response to infection." (PMID 34658838, 2021). "T cell transcription factors regulate specific immune response against pathogen after infection, hence we further studied the activation of different transcription factors STAT-4, STAT-6 after stimulation with M. leprae antigens." (PMID 30642265, 2019).
infection (continued). "Enumeration of lymphocytes, macrophages and polymorphonuclear (PMN) cells revealed greater numbers of macrophages in lung tissue from day 4 to 21 post infection in WT, STAT1−/− and STAT6−/− mice." (PMID 31810203, 2019). "Eighteen hours after infection, we assessed these cultures by immunofluorescence assay (IFA) for phosphorylation and nuclear translocation of STAT6." (PMID 22910631, 2012). "It is of interest that the main Th2 transcription factor STAT6 was upregulated during early infection, while a regulator of Th1 immunity, STAT4, was downregulated in the rabbit lungs at 4 weeks post-infection." (PMID 22645653, 2011). "Peritoneal exudate cells (PEC) were collected 2, 3 and 4 days post-infection and analyzed by Western blot for STAT3 and STAT6 phosphorylation." (PMID 21931552, 2011). "IL-4 can also act on APCs to polarize them during an active infection and it has been shown to up-regulate CD86 on human alveolar macrophages via ERK1/2 and JAK/STAT6 pathways." (PMID 21054882, 2010). "It has been reported that, during the early stage of T. gondii type I and III infection, mouse macrophages tend to M2 phenotype through the STAT3/STAT6 pathways by rhoptry protein 16, while type II infected macrophages tend to M1 phenotype via dense granule protein 15 phosphorylated NF-κB." (PMID 40394721, 2025). "This confirmed that STAT6 signaling was not driving the increased ex vivo reactivation in coinfected mice when HP infection occurs before MHV68 infection." (PMID 37847677, 2023). "The data suggest that despite an increased WT host immune response, STAT6 KO adaptation does not confer any major disadvantage regarding survival or fertility of the adapted N. brasiliensis upon infection of a WT host." (PMID 38079450, 2023). "A recent study showed that mouse models expressing STAT6 developed dorsolateral prostate lobe fibrosis, whereas those lacking STAT6 did not, upon infection with the uropathogenic E. coli strain CP1." (PMID 36201508, 2022). "RT‐qPCR experiments showed that Kp52145 infection increased the levels of the M(Kp) markers arg1, il10, nos2, the ISG isg56 and ido in THP‐1 cells in a STAT6‐dependent manner because the STAT6 inhibitor AS1517499 abrogated Klebsiella‐mediated upregulation of these M(Kp) markers." (PMID 36337046, 2022). "Exogenous activation of STAT3 and 6 suppresses host cell ROS production during infection with ROP16-deficient parasites and depletion of STAT6, but not STAT3 or 5a, causes an accumulation of ROS in cells infected with wild-type parasites." (PMID 33653884, 2021). "Type I or III ROP16 can phosphorylate and activate STAT3 and STAT6 during infection, whereas type II ROP16 does not have this effect." (PMID 32012177, 2020). "The facts that the attenuated cps mutant did not activate STAT6 and did not induce an M2-like state strongly suggest that the induction of an M2-like state is a virulence strategy of Klebsiella to promote infection." (PMID 31796543, 2019). "In our study, phosphorylation of STAT3 and STAT6 transcription factors after infection with T. gondii RH or RHΔrop16 was not different between the OT and Asym groups." (PMID 31867288, 2019). "In the permissive cells Mrc5 and Vero with primary infection of HCMV and HSV1, respectively, we observed that the protein level of STAT6 was gradually inhibited along with the increase expression of lytic genes (IE1/2 in HCMV, ICP0 in HSV1), while ubiquitylated TRIML2 was enhanced." (PMID 30532138, 2018). "Upon infection with L. major IR75, STAT6−/− BALB/c mice developed small lesion, as could be expected from previous reports on murine CL." (PMID 29593739, 2018). "The present study addresses the fundamental question of what the impact would be on the pathological outcome of L. major IR75 infection in the absence of both the IL-12p40 and the STAT6 signaling." (PMID 29593739, 2018).
infection (continued). "It was shown that during H37Rv infection, M1-type markers, phosphorylated STAT1 and iNOS, and M2-type markers, phosphorylated STAT6 and Arg-1, were increased in varying degree, indicating that M. tb infection induced both M1- and M2-type polarization of macrophages." (PMID 28835201, 2017). "We could speculate that the primary infection with a mixed genotype I/II strain, characterized by a high acute virulence and long-term STAT3 and STAT6 activation, partially modulates the immune response upon the challenge with genotype II strain." (PMID 28642841, 2017). "We observed that the absence of a functional STAT6 signaling pathway, which impairs the development of a Th2 response, does not affect the control of infection even in absence of a Th1 response in IL-12p40." (PMID 26376185, 2015). "Infection-induced alterations in ileal AMP expression seen in N. brasiliensis-infected WT mice, including up-regulation of Retnlb and Ang4 and down-regulation of Reg3γ, disappeared almost entirely in IL-13−/− or STAT6−/− mice." (PMID 26377648, 2015). "In contrast, mice with a susceptible genetic background, such as BALB/c, but lacking the STAT6 gene became highly resistant to infection and do not develop AAMs." (PMID 23484125, 2013). "While IRF4 and STAT6 had similarly elevated expressions at 2, 4, 8 and 12 weeks, JAK1 and NFATC4 were upregulated at comparable levels from 2 to 8 weeks and then downregulated at 12 weeks post-infection." (PMID 23448601, 2013). "In addition, except for 4 of the regulatory genes (IRF4, JAK1, NFATC4 and STAT6), many of the other genes in this pathway were only transiently expressed at 2 (IL4R and PTPRC) or 4 and/or 8 (IL13, IL4 and CEBPB) weeks post-infection." (PMID 23448601, 2013). "Unlike that observed with BALB/c WT mice, infection of BALB/c STAT6 −/− mice with VV-HA-IL-4 compared to VV-HA control did not impair the IFN-γ and TNF-α cytokine production capacity of KdA5275–83 or KdF226–34 specific-CD8+ T cells." (PMID 23383283, 2013). "Collectively these data indicate that L. donovani infection induces macrophage STAT6 activation and STAT6-dependent arg1 expression, which do not require but are amplified by type 2 cytokines, and which contribute to impaired control of infection." (PMID 22275864, 2012). "Among the Th2-regulatory genes examined, both STAT6 (signal-transducer and activator of transcription protein-6) and JAK1 (Janus kinase-1) were significantly upregulated at 2 weeks, and STAT6 expression remained high at 4 weeks of infection." (PMID 22645653, 2011). "Infection of STAT6−/− MØ with all three strains failed to induce arginase-1 protein, in contrast to infection of MØ from STAT6+/+ littermates in which we detected ROP16-dependent arginase-1 induction." (PMID 21931552, 2011). "IL-4c-treated Mac-STAT6 mice were not able to trap larvae during secondary infection." (PMID 37018382, 2023). "In the model of Heligmosomoides polygyrus bakeri (Hpb) infection, Mac-STAT6 mice could not trap larvae in the submucosa of the small intestine after secondary infection." (PMID 37018382, 2023). "We also observed changes in the abundance of m6A-modified JAK1 and STAT6 transcripts, which are also part of the JAK/STAT signaling pathway and may functionally interact with each other as part of the host cell response to infection." (PMID 36625663, 2023). "This factor's crucial role is neatly illustrated in Hymenolepis diminuta infection; STAT-6 knockout mice infected with this tapeworm were unable to clear this infection due, in part, to diminished goblet cell response, unlike their IL-13 and IL-4 deficient counterparts at 12 days post-infection." (PMID 33013869, 2020). "However, ulceration was never observed in the footpads of infected STAT6−/− mice over the course of infection." (PMID 29593739, 2018).
infection (continued). "In conclusion, this report shows that in the absence of both STAT6 and IL-12p40 signaling, L. major-infected BALB/c mice remain susceptible to infection but demonstrate higher tolerance to pathogenic threat as they display smaller footpad lesions compared to IL-12p40−/− mice." (PMID 29593739, 2018). "Moreover, in HUVEC cells with KSHV primary infection, more STAT6 consistently translocated into nuclear compartment upon KSHV infection, further supporting the hypothesis that KSHV induces STAT6 nuclear translocation." (PMID 28099521, 2017). "Moreover, exogenous IL-33 treatment did not affect the resistance of Stat6−/− mice to subsequent challenge infection with L. pneumophila." (PMID 28374774, 2017). "While this might have been the case in STAT-6−/− animals in which numbers of IFN-γ+ CD4 cells substantially increased following infection with the mutant virus, it did not hold true for the IL-13−/− mice." (PMID 25751266, 2015). "In relation to the role of STAT-6 in CTL responses, it has been reported that the activation and function of CTL may be impaired in STAT-6−/− mice during infection with the intracellular parasite Toxoplasma gondii, likely as a consequence of reduced levels of CD86 expression on DC." (PMID 25751266, 2015). "Furthermore, when the STAT-6−/− mice used in the previous study were backcrossed to the BALB/c background 10–12 times, they were found to be more susceptible to ECTV-WT infection than WT littermates (data not shown)." (PMID 25751266, 2015). "In a murine model, infection with H. polygyrus and S. mansoni eggs (a complete infectious cycle was not tested) could reactivate the mouse γ-herpes virus MHV68 in vivo, via an IL-4- and Stat6-dependent pathway." (PMID 25398130, 2014). "Interestingly, we detected nuclear accumulation of total STAT6, despite lack of detectable STAT6 tyrosine phosphorylation during ΔROP16 infection." (PMID 21931552, 2011). "To further determine whether the impaired anti-helminth responses in IEC-KO mice were due to defective IEC STAT6 activity, we infected WT, TgSTAT6vt, IEC-KO, IEC-KO-TgSTAT6vt mice with H. poly and analyzed epithelial responses and worm burden in these mice on day 14 after infection." (PMID 36057627, 2022). "However, infection with wild-type (WT) Salmonella did not induce STAT6 phosphorylation." (PMID 31862381, 2020). "Nevertheless, our results indicate that STAT6 signaling in IM does not play an important role in our infection model and suggest that C. neoformans may suppress pro-inflammatory signals further upstream that would otherwise direct the differentiation of IM into fungicidal M1 macrophages." (PMID 30897162, 2019). "However, Stat6 expression is not altered in the absence of STAT2 in super-infection." (PMID 30337919, 2018). "Notably, the increased MHV68 reactivation with preexisting HP infection did not require STAT6 signaling, in contrast to our previous work where HP challenge occurred after MHV68 infection." (PMID 37847677, 2023).
inflammation (13 papers, 2011 to 2023). Aberrant reaction of the microcirculation characterized by movement of fluid and leukocytes from the blood into extravascular tissues. "In the development of allergic airway inflammation, STAT6 activation is very important for Th2 cell-mediated IgE production and the development of airway inflammation and hyperresponsiveness." (PMID 35204186, 2022). "Lack of STAT6 expression in KO mice induced more severe lung inflammation, associated with elevated neutrophil influx and expression of TNF-alpha, IL-6 and IL-1beta in the inflamed lung tissues." (PMID 35606692, 2022). "Moreover, in a mouse model of acute pulmonary inflammation by ovalbumin (OVA) allergen challenge, the expression of genes encoding RELMα and RELMβ in the lung is induced with a signal transducer and activator of transcription 6 (STAT6)-dependent fashion." (PMID 36691020, 2023). "Lack of STAT6 expression in LPS-treated KO mice induced more severe acute lung inflammation than that in LPS-treated WT mice (black arrow)." (PMID 35606692, 2022).
renal disease (4 papers, 2021 to 2026). "On the other hand, other reports suggest that the IL-4 receptor α chain/STAT6 pathway promotes fibrosis and renal disease progression." (PMID 38662181, 2024). "Thus, STAT6 could potentially serve as a therapeutic target for fibrotic renal disease." (PMID 35046382, 2022). "Therefore, targeting STAT6 may provide a novel therapeutic strategy for fibrotic kidney disease." (PMID 34831280, 2021). "The role of STAT6 in kidney disease has not been clearly investigated." (PMID 35046382, 2022).
bacterial infections (2 papers, 2015 to 2023). "The chemokine ccl20b plays an important role in viral and bacterial infections in fish and is upregulated via STAT6 which is stabilized by binding to TRAF6, reducing its ubiquitination." (PMID 37808550, 2023).
intestinal disease (2 papers, 2016 to 2018). "Given the importance of mast cells in intestinal disease additional double mutant CF-animals were tested, one lacking mast cells (C-kitW-sh/W-sh) and Stat6−/− to block IgE production." (PMID 29915289, 2018).
cardiovascular diseases (1 paper, 2013). "Antagonism between the STAT1 and STAT3 pathways is well described, notably in cardiovascular diseases, but reciprocal regulation between STAT1 and STAT6 is an emerging field, and our results may be reflecting such a phenomenon mediated by HDL with regard to macrophage inflammatory state." (PMID 23991225, 2013).
connective tissue tumors (1 paper, 2025). "Staining for B-cell lymphoma 2 (bcl-2, a marker of lymphocytes/undifferentiated cells) and signal transducer and activator of transcription 6 (STAT6, commonly expressed in connective tissue tumors) were weakly positive." (PMID 40065871, 2025).
peripheral neuropathy (1 paper, 2022). A disorder affecting the peripheral nervous system. "The prevention of chemotherapy-induced peripheral neuropathy is correlated with the active IL-4/STAT6 signaling pathway." (PMID 35273508, 2022).
psychiatric disorder (1 paper, 2008). A disorder characterized by behavioral and/or psychological abnormalities, often accompanied by physical symptoms. "Future studies will reveal the etiological role of STAT6, and of other genes of the apoptotic cascade, in major psychiatric disorders." (PMID 20046407, 2008).
STAT6 also shares sentences with these, for which no sentence is quoted: Allergy (19 papers); anaphylaxis (4); myxoid liposarcoma (4); clear cell sarcoma (3); dyslipidemia (3); leiomyosarcoma (3); myeloma (3); neurofibroma (3); oligodendroglioma (3); soft tissue sarcoma (3); type 2 diabetes (3); adenocarcinoma (2); angiomatoid fibrous histiocytoma (2); benign tumor (2); brain infarction (2); chronic atrophic gastritis (2); cutaneous T cell lymphomas (2); desmoid fibromatosis (2); fibrosarcoma (2); glomerulosclerosis (2); Hyperinsulinemia (2); Hypoglycemia (2); inflammatory myofibroblastic tumor (2); kidney injury (2); nodular fasciitis (2); osteoporosis (2); pleomorphic liposarcoma (2); serous ovarian carcinoma (2); undifferentiated pleomorphic sarcoma (2); abdominal aortic aneurysm (1).
A further 127 diseases each share a sentence with STAT6 in 1 paper.